ALB (albumin)
Diseases named in the same sentence as ALB in open-access papers (continued):
Sharing a sentence is not in itself a finding about the gene and the disease.
Sepsis (continued). "During sepsis, albumin’s detoxification and toxin-binding functions are markedly impaired." (PMID 41262247, 2025). "Consequently, a nomogram was constructed incorporating sepsis, human albumin administration, mechanical ventilation, and aminoglycoside usage, utilizing serum creatinine levels as a predictor for assessing the likelihood of AKI in individuals with AHF." (PMID 40124680, 2025). "The extant clinical research has not established a significant direct association between albumin use and renal injury in sepsis patients." (PMID 40841985, 2025). "Therefore, despite ongoing debate, combined crystalloid and albumin therapy remains a viable option for treating sepsis in selected patients." (PMID 41468394, 2025). "The exposure variable was the early administration of albumin following the onset of sepsis." (PMID 40841985, 2025). "However, the guidelines also suggest albumin supplementation in adults with sepsis or septic shock requiring large volumes of crystalloids, although this is a weak recommendation with moderate-quality evidence." (PMID 40841985, 2025). "Subgroup analysis showed a negative association between the albumin infusion and sepsis risk in the AP patients with serum albumin ≤ 3.5g/L (adjusted OR=0.29, 95%CI = 0.08–0.77)." (PMID 40773463, 2025). "Thus, NPAR, which integrates information from both neutrophil activation and albumin depletion, serves as a reliable predictor of mortality and multiple organ failure in sepsis." (PMID 41305720, 2025). "Albumin also has anti-inflammatory, antioxidant, scavenger, and endothelial stabilization properties, which are ideal characteristics in the profound inflammatory response of sepsis." (PMID 40386509, 2025). "Albumin dialysis removes large, albumin-bound toxins mainly found in liver failure patients; its role in sepsis treatment remains unclear, and it is costly." (PMID 40806591, 2025). "As albumin is more costly, this treatment is more likely to have a sepsis billing code." (PMID 39899627, 2025). "Serum albumin, long recognized as a nutritional marker, is increasingly considered a surrogate of endothelial permeability, as its reduction reflects vascular leakage in sepsis." (PMID 40710030, 2025). "It remains unclear whether the potential benefits of albumin for sepsis resuscitation outweigh its documented risks in the context of acute stroke, or how the timing of its administration might influence this balance." (PMID 41468394, 2025). "The net albumin leakage (NAL) from the vascular to the interstitial space may thus represent a quantifiable marker of capillary dysfunction in sepsis." (PMID 40806877, 2025). "Elevated LDH (median 325 mg/dL) and decreased albumin levels (median 26 g/L) may be used as early indicators of sepsis severity." (PMID 40722642, 2025). "Magnesium sulfate’s modulation of ALB metabolism may alleviate sepsis-induced metabolic disturbances." (PMID 40552120, 2025). "While the Surviving Sepsis Guidelines suggest administering albumin in addition to crystalloids for high-volume resuscitation, few studies have examined the impact of this combination for fluid resuscitation or the outcomes of early albumin administration in sepsis." (PMID 40386509, 2025). "ALB, a critical plasma protein, correlates with sepsis severity and inflammation." (PMID 40552120, 2025). "Our study highlights the importance of integrating acute phase markers (e.g., lactate), baseline status indicators (e.g., albumin), and validated clinical scoring systems (e.g., SAPS 3) to improve risk stratification and inform clinical decision making in sepsis." (PMID 41343415, 2025). "When the albumin and saline groups were compared, the relative risk of mortality was 0.87 for patients with severe sepsis and 1.05 for those without severe sepsis." (PMID 40649163, 2025). "Lactate-to-albumin ratio (LAR) is an emergency predictive indicator of sepsis-related mortality." (PMID 40046181, 2025).
Sepsis (continued). "Albumin is a marker of liver synthetic function and may be better for the diagnosis of liver disease in patients with sepsis." (PMID 40149726, 2025). "DSG 2025 (Änderung): Wir schlagen vor, bei Patienten mit Sepsis oder septischem Schock Albumin additiv zu balancierten Kristalloiden zu verabreichen, wenn große Mengen an Flüssigkeit benötigt werden, um eine hämodynamische Stabilität zu erreichen.1(Empfehlungsgrad: schwach)." (PMID 40824313, 2025). "Similarly, in elderly patients with sepsis or COVID-19, albumin emerged as an independent predictor of mortality in a cohort study, indicating higher mortality rates with decreasing albumin levels." (PMID 40155840, 2025). "Furthermore, human albumin has anti-inflammatory and antioxidant properties, the recognition of which has led to the initiation of a clinical trial to investigate changes to these markers in sepsis patients following administration of albumin (NCT03950778)." (PMID 40806286, 2025). "Current research suggests that the lactate/albumin (L/A) ratio may predict multiple organ failure and mortality in critically ill patients, including patients with sepsis." (PMID 40283655, 2025). "The confounders that we adjusted for in our model included age, gender, BMI, CHF, dialysis, bleeding disorder, blood transfusion, SIRS, sepsis/shock, perioperative ventilator dependence, perioperative creatinine, perioperative albumin, perioperative WBC, and perioperative Hct." (PMID 40230736, 2025). "Research suggested that serum albumin trends can predict mortality rates in ICU sepsis patients." (PMID 40041421, 2025). "In contrast, the present study utilized a TTE to demonstrate that albumin use increases the risk of SA-AKI in sepsis patients without impacting 7-day survival." (PMID 40841985, 2025). "It is assumed that maintaining the serum albumin level could have a positive effect on the clinical outcome of sepsis." (PMID 40722642, 2025). "Decreased plasma albumin levels may affect the nutritional status and recovery of patients with sepsis." (PMID 40104144, 2025). "Importantly, the sustained decline in albumin after high-grade CLP accords with clinical evidence, where such a decrease is associated with increased sepsis severity and mortality." (PMID 41155249, 2025). "In addition to being used as an individual prognostic marker, albumin is also combined with other variables to improve the prognostic value of sepsis." (PMID 40307261, 2025). "Importantly, in the multivariable model that included age, albumin, amylase, and sepsis status, N/(LP) remained a statistically significant independent predictor of in-hospital death." (PMID 40722789, 2025). "Currently, albumin therapy was considered to be utilized for addressing hypoproteinemia and conducting fluid resuscitation in critically ill patients, such as those with septicemia and cirrhosis." (PMID 40773463, 2025). "The lactate-to-albumin ratio is a readily quantifiable parameter that has been demonstrated to facilitate prognostication in a variety of critically ill patients, including those with gastrointestinal bleeding and sepsis in the emergency department." (PMID 41343570, 2025). "In addition, the earlier the ALB level is raised to a certain level, the higher the 28-day survival rate of patients with sepsis." (PMID 40438354, 2025). "In light of the intricate interrelationships among sepsis, hypoalbuminemia, and kidney dysfunction, the incorporation of serum albumin and creatinine into sACR may offer a more comprehensive evaluation of alterations in sepsis." (PMID 39564496, 2024). "This suggests that, instead of commonly used heavy metal nanoparticles, including silver, gold, and ceria, the former selenium–human albumin-based nanoparticle inhalant is an excellent candidate in treating lung diseases such as COVID-19 or sepsis-induced lung damage." (PMID 39459897, 2024).
Sepsis (continued). "Furthermore, a cohort study of 946 sepsis patients revealedthat the lactate/albumin ratio was superior to lactatein predicting 28-day mortality." (PMID 39139159, 2024). "In patients with resuscitated sepsis, albumin infusion might lead to greater improvement of tissue hypoperfusion compared to saline." (PMID 38326920, 2024). "Regardless of albumin use, lower body temperature was a risk factor for clinical outcomes in sepsis patients when compared to those with normal or elevated body temperatures." (PMID 39726025, 2024). "Therefore, this current study aims to evaluate the correlation between the serum albumin level and the severity of sepsis in the intensive care unit (ICU) admitted patients." (PMID 39539863, 2024). "In this study, the levels of serum albumin correlate with DVT in patients with sepsis." (PMID 38229151, 2024). "Recently, a study suggested that compared to lactate and albumin alone, the predictor value of the lactate and albumin ratio was outstanding in predicting death and hospital stay (discharge) among sepsis participants, with a sensitivity of 100% and a specificity of 88%." (PMID 38398049, 2024). "Modifiable risk factors for psychiatric impairment post-sepsis include the number of experienced traumatic memories, the length of ICU stay, level of albumin, the use of vasopressors or inotropes, daily activity function after sepsis, and the cumulative dose of dobutamine." (PMID 38381393, 2024). "The prognosis for these patients worsened as serum albumin levels decreased, corroborating previous findings that for every 10 g/L reduction in serum albumin concentration, an increase in the incidence of sepsis, mortality rates, and length of hospital stay was observed." (PMID 39101009, 2024). "Some complications of sepsis may result in renal impairment and decreased albumin levels during the exacerbation phase of the disease; therefore, our findings may be important for clinicians to monitor disease changes and provide timely treatment." (PMID 39013924, 2024). "This research study showed that LA, PRO-BNP, D-dimer, and albumin levels, as well as PT and the presence of pulmonary infection, were independent factors that predicted the need for mechanical ventilation in patients with sepsis within 48 h of admission." (PMID 39498290, 2024). "62.4% patients were hypovitaminosis C. 7 features, including source of infection, the level of serum albumin, age, male gender, sepsis, vascular disease, and wasting of vitamin C by the kidney, were selected using LASSO algorithm and therefore included in the nomogram." (PMID 38429378, 2024). "Hence, it is possible to use the parameters of WBC, CRP and ALB as indicators to estimate the likelihood of sepsis in patients, prior to the acquisition of PCT test results." (PMID 38771840, 2024). "However, despite the established roles of lactate and albumin, the predictive value of L/A ratio in sepsis prognosis remains relatively uncharted, warranting further investigation." (PMID 38518050, 2024). "We previously hypothesized that a positive value of SFA activity of the serum albumin of patients with sepsis was due to albumin fatty acid-binding sites occupied by pre-bound FA derived from the sPLA2-hydrolyzed membrane phospholipids of injured cells." (PMID 39273360, 2024). "Albumin levels predict both short- and long-term sepsis prognosis." (PMID 39498290, 2024). "In currentclinical practice, the lactate level is frequently used todetect the degree of tissue hypoxia and, followingthis, guide the clinical treatment strategy and estimatethe prognosis of sepsis patients.Meanwhile, albumin is a vital serological index reflectingthe severity of inflammation." (PMID 39139159, 2024). "Nevertheless, the testing results for ALB, WBC and CRP could be obtained within a shorter duration comparing to PCT, resulting into an earlier evaluation of sepsis risk in diabetic patients with UTI." (PMID 38771840, 2024).
Sepsis (continued). "The relationship between the serum albumin-to-creatinine ratio (sACR) and mortality in patients with sepsis remains unclear." (PMID 39564496, 2024). "Effective sepsis management was achieved using antibiotics, albumin infusion, and midodrine." (PMID 38707103, 2024). "Lower serum albumin levels were associated with higher SOFA scores, indicating more severe sepsis." (PMID 39539863, 2024). "Albumin is synthesized in the liver; however, serum albumin levels depend not only on the synthetic liver function but on additional factors like the nutritional status, presence of sepsis, systemic inflammatory disorders, and urinary and gastrointestinal losses." (PMID 39597844, 2024). "A reduction in albumin’s binding capacity and alterations in its structure during sepsis could significantly impact its essential physiological functions, potentially affecting patient outcomes." (PMID 39273360, 2024). "Levels of serum albumin correlated with DVT in patients with sepsis (p value 0.003)." (PMID 38229151, 2024). "This prospective study on patients with sepsis highlights that albumin infusion compared to saline might lead to greater improvement of tissue perfusion." (PMID 38326920, 2024). "Predicated on the control of confounding factors,six studies evaluated whether lactate/albumin ratio could be used as an independentrisk factor for mortality in sepsis patients." (PMID 39139159, 2024). "Furthermore, albumin has also been recognized for its capacity to bind several inflammatory mediators, exhibiting an immunomodulatory effect in systemic inflammation and sepsis via toll-like receptor-mediated signaling." (PMID 38542094, 2024). "Sepsis patients with concurrent liver failure may exhibit hyperlactatemia or decreased albumin levels." (PMID 39139160, 2024). "This study aims to explore the intricate relationship between initial serum albumin concentrations and the subsequent clinical prognosis of individuals admitted with sepsis, contributing to a nuanced understanding of the factors influencing outcomes in this critical healthcare scenario." (PMID 38826606, 2024). "Therefore, further research is warranted to validate these results and delve deeper into the underlying mechanisms driving the relationship between serum albumin levels and sepsis severity." (PMID 39539863, 2024). "This study also showed that serum albumin of patients with sepsis had much higher activity in the Alb-FA-BA assay compared with the healthy subject serum, suggesting alterations in the structure and binding properties of septic patients’ serum albumin." (PMID 39273360, 2024). "Age ≥ 70 years, recent antibiotic use, history of invasive operations within the last 2 weeks, hepatic artery embolization, decreased albumin, high APACHE II scores and elevated serum SAA and BLA levels are independent risk factors for sepsis in liver cirrhosis patients." (PMID 39039452, 2024). "By evaluating serum albumin levels at the point of admission, the research aims to illuminate the potential significance of this biomarker in predicting and influencing the trajectory of sepsis cases within the ICU setting." (PMID 38826606, 2024). "Therefore, this study recommends the development of guidelines incorporating serum albumin level as a prognostic indicator for sepsis severity." (PMID 39539863, 2024). "Consequently, investigating the variations in serum albumin levels among ICU sepsis patients through trajectory modeling becomes a pivotal step." (PMID 39101009, 2024). "A predefined subgroup analysis also found a lower, though not statistically significant, risk of death in the albumin group among patients with severe sepsis." (PMID 38730983, 2024). "The levels of serum albumin correlated with DVT in patients with sepsis (p value 0.003)." (PMID 38229151, 2024). "Similarly, serum albumin concentration has recently been postulated as a predictive biomarker of mortality in sepsis." (PMID 39252713, 2024).
Sepsis (continued). "To address these issues, we aimed to evaluate the association of CKD, defined by both estimated glomerular filtration rate (eGFR) < 60 ml/min/1.73m2 and albuminuria (urinary albumin–creatinine ratio (ACR) ≥ 3 mg/mmol, with the risk of and mortality from sepsis and bloodstream infections (BSI)." (PMID 38679665, 2024). "Additionally, this investigation addresses a knowledge gap regarding the prognostic impact of albumin level fluctuations in patients with sepsis when albumin exceeds 30 g/L, thus providing a data-driven foundation for future therapeutic interventions." (PMID 39101009, 2024). "Notably, in a cohort study, albumin emerged as an independent predictor of mortality in elderly sepsis cases." (PMID 38195421, 2024). "Collectively, these mechanisms underscore the critical role of serum albumin in maintaining vascular integrity, coagulation homeostasis, and inflammatory balance, highlighting the importance of monitoring and supplementation of albumin in sepsis management." (PMID 39539863, 2024). "Our research has the potential to contribute to hypothesis generation on the role of albumin in the management of sepsis." (PMID 39459557, 2024). "In their systematic review and sequential network meta-analyses of resuscitation fluid types in sepsis, surgical, and trauma patients, Tseng et al73 concluded that balanced crystalloids and albumin reduced mortality more effectively than laevorotatory HES (L-HES) and saline in septic patients." (PMID 40041106, 2024). "However, a recent prospective study in 50 patients with prolonged peripheral hypoperfusion showed that albumin infusion (20% 100 mL) improved tissue perfusion more than isotonic saline in resuscitated sepsis patients." (PMID 38658435, 2024). "Thus, this study aimed to explore theassociation between the lactate/albumin ratio and theprognosis of sepsis patients using meta-analysis." (PMID 39139159, 2024). "When the adjustment parameter was lambda.min (λ = 0.033), 7 features with nonzero coefficients were selected as important indices for the prediction of hypovitaminosis C, including source of infection, sepsis, serum albumin, age,male gender, wasting vitamin C by kidney, and vascular disease." (PMID 38429378, 2024). "The independent factors related to the risk of requiring mechanical ventilation in patients with sepsis within 48 h included lactic acid, pro-brain natriuretic peptide (PRO-BNP), and albumin levels, as well as prothrombin time, the presence of lung infection, and D-dimer levels." (PMID 39498290, 2024). "Fourth, it would be interesting tocompare the value of lactate/albumin ratio and lactatein predicting the prognosis of patients with sepsis.However, due to the limited data and published literature presently, no comparative study could becarried out." (PMID 39139159, 2024). "Likewise, the total deficiency of a spermidine effect on the FA binding capacity in albumin in the sera of patients with sepsis with positive SFA activity suggests the saturation of pre-bound FA in the serum albumin of patients with sepsis." (PMID 39273360, 2024). "Therefore, this study was designed to determine the predictive capacity of serum albumin levels for the severity of sepsis in intensive care unit (ICU) patients." (PMID 39539863, 2024). "The analysis of binding coefficients and binding efficiency performed in our study, which provide clues about the molecular flexibility of the albumin molecule, suggested a detectable reduction in the molecular flexibility of albumin in patients with sepsis compared with the control group." (PMID 37628734, 2023). "Insights from the effectiveness of albumin in cirrhosis could inform its use in other conditions, including sepsis." (PMID 38139434, 2023). "In addition, the ALBIOS study reported that albumin infusion doesn’t improve the 28-day and 90-day mortality rates for sepsis patients." (PMID 37277756, 2023).